ISL1 (ISL LIM homeobox 1)
Diseases named in the same sentence as ISL1 in open-access papers (continued):
Sharing a sentence is not in itself a finding about the gene and the disease.
pancreatic cancer (2 papers, 2017 to 2019). "We also found that ISL1 could upregulate cyclin D1, cyclin B, and c-Myc, which was in agreement with previous reports on pancreatic cancer cells." (PMID 30674889, 2019).
Tetralogy of Fallot (2 papers, 2014 to 2023). A congenital cardiac malformation comprising pulmonary stenosis, overriding aorta, ventricular septum defect, and right ventricular hypertrophy. "From a population base of 974,579 births during 1999–2004, we used multiplex ligation-dependent probe amplification to screen for microdeletions/duplications of ISL1 among 389 infants with tetralogy of Fallot or d-transposition of the great arteries (d-TGA)." (PMID 25077177, 2014).
Alzheimer disease (1 paper, 2014). A progressive, neurodegenerative disease characterized by loss of function and death of nerve cells in several areas of the brain leading to loss of cognitive function such as memory and language. "Could Alzheimer disease and amyotrophic lateral sclerosis, two human pathologies affecting cholinergic neurons, involve a loss of Isl1-Lhx3 and Isl1-Lhx8 function?" (PMID 24762739, 2014).
angioleiomyoma (1 paper, 2018). A benign, slow-growing neoplasm that arises from the dermis or subcutaneous tissue. "Only six genes show significant differences between the angioleiomyoma types (ISL1, NCSTN, TCF7, WNT10A, WNT11, WNT7A) but their relative expression levels were very low, which indicates no biological relevance (< 0.4 compared to standardized reference gene index)." (PMID 29881541, 2018).
aortic stenosis (1 paper, 2019). Aortic valve stenosis is a aortic valve disease caused by the incomplete opening of the aortic valve. "Wholemount and histological analyses of Isl1 hypomorphic embryos at E12.5 and E17.5 revealed various degrees of cardiac outflow tract (OFT) septation abnormalities, including partial OFT septal defects with aortic stenosis and misalignment and persistent truncus arteriosus (PTA)." (PMID 31024170, 2019).
atrial fibrillation (1 paper, 2023). A disorder characterized by an electrocardiographic finding of a supraventricular arrhythmia characterized by the replacement of consistent P waves by rapid oscillations or fibrillatory waves that vary in size, shape and timing and are accompanied by an irregular ventricular response. "Decreased expression of the ISL1 gene has been reported to be associated with many cardiovascular diseases in human, such as CHDs, atrial fibrillation, and dilated cardiomyopathy." (PMID 36830727, 2023).
Bradycardia (1 paper, 2013). A slower than normal heart rate (in adults, slower than 60 beats per minute). "In addition, deficiency of both Isl1 and Shox2 in fish, as well as Shox2 deficiency in the mouse results in a bradycardia phenotype." (PMID 23455426, 2013).
Burkitt lymphoma (1 paper, 2014). A rare form of malignant mature B-cell non-Hodgkin lymphoma. "Meanwhile, although strong positive staining for ISL-1 was identified in 25% of 8 follicular lymphoma (FL) and 67% of 3 Burkitt lymphoma samples, respectively, the total numbers of those specimens examined were small and awaited larger confirmatory studies." (PMID 25070240, 2014).
chronic otitis media (1 paper, 2011). Chronic form of otitis media (disease). "We report that the low penetrance hearing impairment of dearisch mutants is associated with chronic otitis media and by using exome sequencing we have identified the likely causative mutation in the gene Islet 1 (Isl1)." (PMID 21936904, 2011).
colon cancer (1 paper, 2019). "Given that ZEB1 promotes the stemness and invasiveness of pancreatic and colon cancer cells via activation of EMT45,46, our results indicated that the tumorigenic role of ISL1 may be achieved, at least partially, through activation of ZEB1 in GC." (PMID 30674889, 2019).
Cushing syndrome (1 paper, 2023). Cushing's syndrome (CS) encompasses a group of hormonal disorders caused by prolonged and high exposure levels to glucocorticoids that can be of either endogenous (adrenal cortex production) or exogenous (iatrogenic) origin. "Biologically and structurally distinct from these RenNETs are the ACTH-positive RenNETs associated with an ectopic Cushing syndrome and displaying a typical solid-eosinophilic morphology in the absence of ISL1 or SATB2 expression." (PMID 37405461, 2023).
dental caries (1 paper, 2012). The decay of a tooth, in which it becomes softened, discolored, and/or porous. "In mice, this gene is exclusively expressed in epithelial cells of developing incisors, and is a crucial regulator of jaw and tooth development, suggesting a possible mechanism through which ISL1 may affect susceptibility to dental caries." (PMID 23259602, 2012).
diabetes type I (1 paper, 2018). "The multiplicity of ISL1 function is mirrored by its role in different diseases, such as BEEC, diabetes type I/II, and congenital heart defects." (PMID 30563179, 2018).
duodenogastric reflux (1 paper, 2014). Retrograde flow of duodenal contents (bile acids; pancreatic juice) into the stomach. "Further evidence that Isl1 is required for formation and growth of the pylorus was that duodenogastric reflux, which results from reduced contractile activity of the pyloric sphincter, was clearly observed in Isl1MCM/Del stomachs." (PMID 24674670, 2014).
glaucoma (1 paper, 2018). Increased pressure in the eyeball due to obstruction of the outflow of aqueous humor. "LMX1B gene encodes LIM (Lin-1, Isl-1, and Mec-3)-homeodomain transcription factor 1 beta, and rare deleterious mutations in LMX1B cause NPS, with glaucoma being one of the manifestations of the syndrome." (PMID 29891935, 2018).
hearing loss (1 paper, 2021). "The expression of Tub and Znf532 was also regulated by Isl1; Isl1 is essential for the development of pacemaker cells and helps to prevent age-related and noise-induced hearing loss." (PMID 34819838, 2021).
heart failure (1 paper, 2020). Inability of the heart to pump blood at an adequate rate to meet tissue metabolic requirements. "In summary, we have identified five factors that could be involved in the downregulation of HCN4 in the sinus node in heart failure: Isl1, NRSF, Tbx18, miR-139-3p and miR-370-3p." (PMID 32647133, 2020). "In the heart failure mice, qPCR showed no significant change in Bmp2, Bmp4, Nkx2.5, Shox2 and Tbx3 in the sinus node, but there was a significant downregulation of Tbx18 and Isl1 and upregulation of AP1, Mef2c and NRSF mRNA." (PMID 32647133, 2020). "Of the transcription factors known or predicted to regulate HCN4 (AP1, Isl1, Mef2c, Nkx2.5, NRSF, Tbx3 and Tbx18), two (Nkx2.5 and Tbx3) did not change in the sinus node in heart failure." (PMID 32647133, 2020).
Hydrocephalus (1 paper, 2023). Hydrocephalus is an active distension of the ventricular system of the brain resulting from inadequate passage of CSF from its point of production within the cerebral ventricles to its point of absorption into the systemic circulation. "This suggests that hydrocephalus might begin during embryonic development and that Isl1-expressing progenitors could be required for cerebrospinal fluid homeostasis." (PMID 37470706, 2023). "Skull doming in G9afl/fl;Isl1-Cre mice is likely secondary to hydrocephalus and not due to defective ossification because the thickness of the frontal bone was normal in mutant embryos." (PMID 37470706, 2023).
Hyperinsulinemia (1 paper, 2016). An increased concentration of insulin in the blood. "The higher expression of PIASy and Isl1 may be a cause of hyperinsulinemia." (PMID 28000708, 2016).
Hypertension (1 paper, 2024). The presence of chronic increased pressure in the systemic arterial system. "In the hypothalamus of WAG rats, Npas4 gene expression correlates statistically most significantly with the expression of other DEGs, among which the Bcl2l1 gene is associated with hypertension and four DEGs encode TFs (Isl1, Hnrnpr, Mlxipl, and Zfp189)." (PMID 38928385, 2024).
hypertrophic pyloric stenosis (1 paper, 2014). An abnormality characterized by thickening of the muscle in the wall of the pylorus. "Isl1 expression was also examined by immunofluorescence in human hypertrophic pyloric stenosis where the majority of smooth muscle cells were found to express Isl1." (PMID 24674670, 2014).
imbalance (1 paper, 2022). "We therefore cannot fully exclude that Meis2 recombination also occurs in some of these central neuronal populations that somehow participate in the autonomic imbalance we report in Isl1+/CRE::Meis2LoxP/LoxP mice." (PMID 36418415, 2022).
Impaired glucose tolerance (1 paper, 2022). An abnormal resistance to glucose, i.e., a reduction in the ability to maintain glucose levels in the blood stream within normal limits following oral or intravenous administration of glucose. "Furthermore, deletion of ISL1 in the intestine causes reduced expression levels of incretin hormones glucagon-like peptide-1 and glucose-dependent insulinotropic polypeptide, thus contributing to lipid malabsorption and impaired glucose tolerance." (PMID 35100965, 2022).
leishmaniasis (1 paper, 2024). Infectious disease that is transmitted through the bite of hematophagous female phlebotomine sand flies. "Another transcription factor which was enriched through TFTG network was Isl1, although much is not known about the role of this gene in leishmaniasis." (PMID 38299832, 2024).
liver steatosis (1 paper, 2022). "Results from Oil red O and HE staining showed that overexpressing ISL1 reduced the degree of liver steatosis, reduced the volume of liver cells in liver tissues with fewer lipid vacuolation accompanied by decreased TG and TC contents." (PMID 35100965, 2022). "We verified that transcription factor ISL1 cooperated with demethylase KDM6B to upregulate lipid metabolizing enzyme SNAI1, so as to protect against improve NAFLD, including reducing the degree of hepatic steatosis, plasma lipid concentration, and lipid accumulation in cells." (PMID 35100965, 2022).
lymph node metastasis (1 paper, 2019). "Here we have shown that ISL1 expression was positively correlated with lymph node metastasis, vascular invasion, distant metastasis, and more advanced TNM stage in GC." (PMID 30674889, 2019). "GC patients with diffuse type, lymph node metastasis, vascular invasion, and distant metastasis exhibited higher expression levels of ISL1 than those without these characteristics (P < 0.001 for all parameters)." (PMID 30674889, 2019).
morbid obesity (1 paper, 2020). An excess of body weight, normally defined as an individual with a body mass index greater than 35 or a body weight greater than one hundred percent of ideal body weight. "A linkage analysis in French families with morbid obesity showed linkage between ISL1 and BMI and leptin." (PMID 32153512, 2020).
myxoma (1 paper, 2020). A benign soft tissue neoplasm characterized by the presence of spindle and stellate cells, lobulated growth pattern, and myxoid stroma formation. "Also, these clonogenic c-kitpos/CD45neg/CD31neg myxoma-derived CSCs express OCT-4, NANOG, BMI-1, NKX2.5, and ISL-1 and form cardiospheres at a rate similar to normal human CSCs even though serial spherogenesis was reduced." (PMID 32330934, 2020).
ovarian carcinoma (1 paper, 2024). A malignant neoplasm originating from the surface ovarian epithelium. "Using experimental data obtained on ovarian carcinoma cells using a PageRank-based algorithm, the super-enhancer regulator ISL1 is predicted to be the driving force behind this plasticity." (PMID 38542080, 2024). "Cell-type-specific transcription-factor ISL1, an SE regulator in ovarian cancer cells, apparently is the main driver of SE plasticity induced by cisplatin treatment." (PMID 38542080, 2024). "Alternative examples of autoregulation have been found for the following master TFs: FOSL1 in HNCC, MYC in colorectal cancer, ASCL1 in small lung adenocarcinoma, ISL1 in ovarian cancer, FOXC1 in triple-negative breast cancer, and MYCN in MYCN-amplified neuroblastoma." (PMID 38542080, 2024).
pituitary tumours (1 paper, 2015). "On this basis, we reasoned that the differences in methylation frequency observed for HOXA9 and ISL1 may be consequent to different clinical characteristics and/or outcomes within our HG tumour cohort; a phenomenon similarly described in, for example, breast, colon and pituitary tumours." (PMID 26332997, 2015).
renal carcinoma (1 paper, 2022). A carcinoma arising from the epithelium of the renal parenchyma or the renal pelvis. "As we expected, both of these drugs significantly decreased the proliferation rate of tumor cells and the expression levels of HOXC5, ISL1, and VENTX in two renal cancer cell lines." (PMID 35853872, 2022).
respiratory failure (1 paper, 2024). The significant impairment of gas exchange within the lungs resulting in hypoxia, hypercarbia, or both, to the extent that organ tissue perfusion is severely compromised. "Mice lacking ISL1 expression also die shortly after birth due to respiratory failure and lack of diaphragm innervation." (PMID 38689650, 2024).
steatosis (1 paper, 2022). Increased lipid within the cytoplasm of cells. "To validate the effect of ISL1, we used a murine model and the results confirmed that overexpressing ISL1 attenuated lipogenesis and steatosis after NAFLD models were established." (PMID 35100965, 2022). "In this study, we identified that ISL1 had interacted with H3K27me3 demethylase KDM6B to promote the expression of SNAI1, by which lipogenesis and steatosis were attenuated while lipolysis was promoted in the mice models of NAFLD." (PMID 35100965, 2022). "Oil red O staining showed that knocking down KDM6B while overexpressing ISL1 inhibited steatosis, while knocking down ISL1 while overexpressing KDM6B did not inhibit steatosis." (PMID 35100965, 2022).
thyroid (1 paper, 2021). "Novel neuroendocrine and C cell markers, such as INSM-1, ISL1, secretagonin, and FOXA1, are upcoming in thyroid oncopathology practice and under investigation." (PMID 35008368, 2021).
urothelial carcinoma (1 paper, 2020). A malignant neoplasm derived from the transitional epithelium of the urinary tract (urinary bladder, ureter, urethra, or renal pelvis). "A total of 100 formalin-fixed paraffin-embedded urothelial carcinoma tissues were selected from the Department of Pathology, Hospital Kuala Lumpur and the protein expression of ISL1 and LHX5 was determined using immunohistochemistry." (PMID 32158343, 2020). "In general, the immunohistochemical protein expression characteristics of ISL1 and LHX5 reflect their potential roles in urothelial carcinoma of the bladder tumourigenesis." (PMID 32158343, 2020).
urothelial carcinoma of the bladder (1 paper, 2020). "Our study showed decreasing ISL1 expression as the grade of the urothelial carcinoma of the bladder increased which supports the methylation data of previous studies." (PMID 32158343, 2020). "In this study, we demonstrate that ISL1 expression increases with the stage of urothelial carcinoma of the bladder." (PMID 32158343, 2020). "ISL1 and LHX5 expression was found across all tumour grades and stages of urothelial carcinoma of the bladder." (PMID 32158343, 2020). "However, further functional studies of the protein need to be done to confirm the functional significance of the expression and role of ISL1 and LHX5 in urothelial carcinoma of the bladder." (PMID 32158343, 2020).
ventricular septal defect (1 paper, 2021). The presence of a defect (opening) in the septum that separates the two ventricles of the heart. "We describe the findings of genotyping the polymorphisms in the MTRR, GATA4, VEGF and ISL1 genes in Pakistani children with isolated ventricular septal defects." (PMID 33757570, 2021).
tumor (28 papers, 2014 to 2026). "Conversely, there is an increase in Acvr1, Zfp703, Isl1, and Tcf712, suggesting that ephrinB2 loss shifts the tumor microenvironment (TME) toward a less invasive phenotype." (PMID 39489818, 2025). "Since ISL1-positive expression is associated with vascular invasion, tumor depth, and lymph node invasion in GC patients, it is possible that ISL1 promotes more aggressive behaviors in GC cells." (PMID 30674889, 2019). "In previous reports, HOXA9 and ZNF154 methylation has been associated with tumour recurrence, and ISL1 methylation with tumour progression in predominantly low/intermediate-grade tumours." (PMID 26332997, 2015). "Since our findings support previous associations of HOXA9 and ISL1 methylation with tumour characteristics and behaviour, we appraised potential clinical correlates of HOXA9 and ISL1 methylation, including their prognostic potential." (PMID 26332997, 2015). "Additionally, previous studies suggested that ISL1 is highly expressed in gastric and breast cancer and is associated with advanced tumor invasion, proliferation, migration, tumor stage, tumor size, metastasis, and poor overall survival." (PMID 31885629, 2019). "The highest overexpressed gene in ROS1+ tumor specimens and cell lines, ISL1 provides new insights about this molecular subtype." (PMID 39737401, 2024). "The shared traits offer a new insight about the most representative features of cell lines’ tumor physiology, shown by a dependency on ISL1 expression which links its activity with glucose metabolism and the acquisition of a mesenchymal phenotype." (PMID 39737401, 2024). "We further confirmed that knocking down two TFs (HOXC5 and ISL1) strongly reduced tumor growth in the xenograft mouse models." (PMID 35853872, 2022). "Our results demonstrate that ISL1 downregulation can effectively inhibit tumor growth in a xenograft model of human CRPC." (PMID 34753990, 2021). "We previously reported that ISL1 is highly expressed in GC and is correlated with advanced tumor-nodes-metastasis (TNM) stage, lymph node metastasis, and poorer overall survival." (PMID 33962568, 2021). "Our results demonstrate that ISL1 promoted tumorigenesis through increasing tumor weight and volume in vivo, which are in good agreement with the results in vitro." (PMID 34131100, 2021). "Further, ISL1 enhanced tumor growth and targeted the downstream genes CCNB1, CCNB2, and C-myc in GC." (PMID 33962568, 2021). "We compared the increase in tumor volume over 30 days and found that the xenografts from ISL1 knockdown cells showed hardly any increase in size, whereas control shRNA-expressing cells exhibited continuous tumor growth." (PMID 34753990, 2021). "The proportion of tumours expressing high levels of ISL1 was found to be highest in later stage tumours." (PMID 32158343, 2020). "The high percentage of tumours expressing both these genes suggests that ISL1 and LHX5 play an important role in bladder tumourigenesis across multiple stages." (PMID 32158343, 2020). "Comparatively, mice injected with a mixture of cells with lentivirus-mediated overexpression of ISL1 exhibited a 210% increase in tumor weight compared with mice injected with corresponding control cells." (PMID 30674889, 2019). "In summary, this study demonstrates that OCT4 is involved in tumour‐proliferative capacity by modulating DNMT1/ISL1 expression and ERK signalling pathway." (PMID 31012189, 2019). "We found that ISL1 expression was correlated to tumour size, molecular subtype, ER, PR, HER2 and Ki67 status." (PMID 31012189, 2019). "We recently reported that ISL1 is highly expressed in GC and is correlated with advanced tumor-nodes-metastasis stage, lymph node metastasis, and poorer overall survival." (PMID 27183908, 2016). "Meanwhile, the tumor volumes formed by the ISL1-knockdown cells were obviously reduced at day 24 (0.34 ± 0.48 cm3 vs. 3.20 ± 1.26 cm3, p < 0.05)." (PMID 27183908, 2016).